BRAF (B-Raf proto-oncogene, serine/threonine kinase)
Diseases named in the same sentence as BRAF in open-access papers (continued):
Sharing a sentence is not in itself a finding about the gene and the disease.
melanoma (continued). "The most common oncogenic BRAF mutation in melanomas, V600E (formerly called V599E), results in constitutive ERK signalling in vivo and can transform immortal fibroblasts and immortal mouse melanocytes." (PMID 16880792, 2006). "On the other hand, strong ID1 expression was associated with thicker primary tumours and presence of BRAF mutations, as well as with significantly reduced patient survival, indicating an important role in melanoma progression." (PMID 16189525, 2005). "We noted that among the 7 melanomas arising from the head and neck region, only 1 harbored a BRAF mutation." (PMID 15613230, 2004). "This is consistent with the idea that activating BRAF mutations affect the pattern of metastatic spread in melanoma, although we await confirmation of these findings in a prospective study." (PMID 15613230, 2004). "Melanomas harboring BRAF mutations were more likely to metastasize to liver (P = 0.02) and to metastasize to multiple organs (P = 0.048)." (PMID 15613230, 2004). "High frequency of BRAF mutations has been reported in malignant melanoma, however, there has been little clinical correlation data elucidating the biological effects of these mutations in patients." (PMID 15613230, 2004). "Recently, activating BRAF mutations were found with high frequency in malignant melanomas, including primary tumors and cell lines." (PMID 15613230, 2004). "Larger prospective studies are required to verify these observations and to clarify other biological consequences of BRAF mutations in melanoma." (PMID 15613230, 2004). "Kumar and colleagues found that melanoma patients with BRAF mutations showed a statistically significant diminished duration of response to treatment compared to those without the mutations." (PMID 15613230, 2004). "Since little information was available on the biological effects of activating BRAF mutations in melanoma, we analyzed the clinical characteristics of 68 melanoma patients whose tumors we had previously analyzed for BRAF." (PMID 15613230, 2004). "Whereas the malignant melanoma is the most common tumour with BRAF mutations (roughly 60%), this tumour is known to possess a much lesser frequency of RAS mutations." (PMID 14612909, 2003). "There are isolated reports of BRAF inhibitor use in pregnancy-associated stage IV melanoma." (PMID 41209431, 2026). "Initially diagnosed with BRAF V600E-mutated melanoma, he received Dabrafenib and Trametinib." (PMID 41929554, 2026). "Molecular approaches able to detect rare BRAF mutations could identify additional melanoma cases eligible for therapies with BRAF/MEK inhibitors." (PMID 42003243, 2026). "We summarize the structure, glycosylation and regulation of CD24, then discuss its role in melanoma, supporting phenotypic plasticity, sustaining stem-like populations and promoting resistance to BRAF-targeted and cytotoxic therapies through SOX2/STAT3-linked programmes." (PMID 42126185, 2026). "All these are key to improving the survival of patients with BRAF/NRAS mutation melanoma." (PMID 41492362, 2026). "This review explores the molecular mechanisms regulating signaling pathways that may be potentially involved in modulating apoptosis in melanoma tumor cells harboring mutations in BRAF, NRAS, and NF1 genes." (PMID 42193039, 2026). "Only part of BRAF mutation melanoma patients can benefit from BRAF inhibitor, and these patients with objective response may rapidly develop secondary resistance." (PMID 41492362, 2026). "Adjuvant therapy with D/T may represent the most effective treatment strategy for Chinese patients with stage III melanoma harboring BRAF V600 mutations." (PMID 42039710, 2026). "Additionally, NRAS mutation melanoma tends to have a thicker tumor (median thickness of about 3.7 mm) based on Breslow depth compared with BRAF mutation or NRAS/BRAF wild‐type." (PMID 41492362, 2026).
melanoma (continued). "RAS/RAF/MEK/ERK1/2 mitogen-activated protein kinase (MAPK) pathway-based treatments, typically combination therapies with inhibitors for oncogenic BRAF V600 (BRAFi) and MEK1/2 (MEKi), are important treatment alternatives to immunotherapy in advanced BRAF-mutated melanoma." (PMID 41916083, 2026). "However, the approval of this combination by the Portuguese Regulatory Authority occurred 76 months after its approval by the European Authority, leaving tyrosine kinase inhibitors as the only 1L option available for the BRAF-mutated melanoma population." (PMID 40027067, 2025). "However, only 68% of patients with BRAF‐mutated melanoma respond to BRAF + MEK inhibitors, with a median duration of response of 13.8 months." (PMID 40898695, 2025). "Also, Spitz melanomas are thought to generally have a more favourable prognosis than melanomas with BRAF, NRAS, or NF1 mutations." (PMID 40107205, 2025). "Gained therapies included tyrosine kinase inhibitors (TKIs) in the context of EGFR-mutated NSCLC, trastuzumab deruxtecan for ERBB2-mutated NSCLC, ivosidenib for IDH1-mutated CCA, MEK and RAF inhibitor combination therapies for BRAF V600E melanomas, and PARP inhibitors for BRCA2-mutated HGSOC." (PMID 40399445, 2025). "BRAF V600E mutations have also been reported in nodal nevi from patients with stage II melanoma." (PMID 40507250, 2025). "Additionally, relapse-free survival in all malignant melanomas is longer in patients with BRAF V600E mutation than in those with BRAF V600K/V600R mutations." (PMID 40320509, 2025). "There is still debate on which systemic therapy is the best for BRAF-mutated melanomas, and further research is needed to discover what clinical parameters or biomarkers could indicate the prognosis and guide the choice of the best therapy in each case." (PMID 41010758, 2025). "At the molecular level, melanoma pathogenesis is driven by genetic alterations in pathways that regulate proliferation, differentiation and apoptosis, with recurrent mutations in genes such as BRAF, NRAS, NF1, KIT, TERT, and CDKN2A." (PMID 41011113, 2025). "Further, while we chose SK-MEL-5 cells as a representative of melanoma cells due to their BRAF mutation and cellular morphology, a difference between this cell line and other established lines is that the donor was significantly younger (24 years old) and has a CDKN2A mutation." (PMID 40428399, 2025). "Additionally, MC1R variants heighten susceptibility to UV-induced melanoma through oxidative stress and mutations in genes like BRAF and NRAS." (PMID 39859464, 2025). "In contrast, high-CSD melanomas frequently lack BRAF V600E mutations but may have alterations in genes such as NRAS, NF1, and KIT while exhibiting a higher TMB." (PMID 40125165, 2025). "Consequently, it is recommended that all patients with malignant melanoma be screened for the BRAF V600E mutation, as this opens the possibility for treatment with BRAF inhibitors, such as dabrafenib, trametinib, and vemurafenib." (PMID 40236344, 2025). "Also, in another study on this topic, plasma ctDNA BRAF V600E/K mutations were analyzed using ddPCR in 19 melanoma patients treated with BRAF/MEKi, and ddPCR negativity was confirmed with ultra-deep sequencing." (PMID 39859576, 2025). "BRAF V600E mutations confer sensitivity to BRAF/MEK inhibitors but may diminish immunotherapy responses in melanoma, highlighting mutation-dependent trade-offs in treatment efficacy." (PMID 40808963, 2025). "More recently, the same authors published a multicentric study using the same method to analyze cfDNA from 66 advanced BRAF V600E/K melanoma patients treated with dabrafenib, in which BRAF mutation in pre-cfDNAs was associated significantly with tumor burden, PFS and OS (p < 0.05)." (PMID 39859576, 2025).
melanoma (continued). "In one study, allele-specific qPCR analysis for detecting BRAF V600 E/E2/D/K/R/M (Idylla) mutations on ctDNA was used to analyze plasma samples of patients with known BRAF V600-mutant melanoma treated with dabrafenib and trametinib in a phase II trial (n = 36 patients)." (PMID 39859576, 2025). "These alterations are common in BRAF-mutant melanoma and are associated with shorter survival." (PMID 40332392, 2025). "Therefore, adjuvant TT for patients with BRAF V600 mutated melanoma and ICI for BRAF wild-type and BRAF V600 mutated melanoma can be considered." (PMID 39673834, 2025). "Real-world data suggest that adjuvant TT may be associated with better RFS and DMFS in stage III BRAF V600-mutated melanoma compared to ICI." (PMID 39673834, 2025). "Recommendation 8: Molecular testing to detect mutations in the BRAF gene is recommended in the scenario of patients with high-risk stage II, 3 and 4 melanoma, using a sample with adequate neoplastic representation and a molecular technique duly validated by the laboratory." (PMID 40614549, 2025). "We are aware that with the rapid development of melanoma drugs, patients with cutaneous melanoma, due to their high tumor mutational burden and a high proportion of BRAF mutations (at least 50%), have shown a more favorable prognosis compared to other subtypes." (PMID 41278268, 2025). "Stage III/IV melanoma had the highest odds of being BRAF mutated." (PMID 40902091, 2025). "For example, in melanomas bearing mutated BRAF, p66Shc may increase the sensitivity of the cells to oxidative stress‐induced apoptosis and may function as a tumour suppressor." (PMID 40690563, 2025). "However, Thielmann CM's research shows that TERT promoter mutations are associated with longer asymptomatic survival in BRAF mutant melanoma patients treated with BRAF and MEK inhibitors." (PMID 39871386, 2025). "This MITF-PGC1 axis connects BRAF mutation to mitochondrial dysfunction in melanoma." (PMID 40872623, 2025). "Pathogenic gene variants in the BRAF gene occur in about 50% of patients with melanoma." (PMID 40981345, 2025). "BRAF mutation was more frequently observed in ulcerated melanomas with a high mitotic rate ≥ 5 n/mm2 (a measure of how fast melanoma cells are growing), while NRAS mutation was associated with amelanotic/hypomelanotic (subtype with little or no pigmentation) and nodular melanoma." (PMID 40867317, 2025). "It has been reported that activating mutations in BRAF or c-KIT may be present in malignant melanoma, which has important implications for the tumor’s response to anticancer drugs targeting BRAF or c-KIT." (PMID 40641936, 2025). "Investigation of molecular features of brain metastases in BRAF-mutated vs. BRAF-wildtype melanomas may lead to new insights in tumor biology and may yield new therapeutic approaches." (PMID 40028330, 2025). "Low-CSD melanomas often harbor BRAF V600E mutations and have a lower TMB." (PMID 40125165, 2025). "BRAF-mutated genotype was associated with lower survival, particularly in stage II melanoma." (PMID 40902091, 2025). "In the phase II, single-arm NeoCombi study, patients with resectable BRAF-mutated stage IIIB-C melanoma received 12 weeks of neoadjuvant targeted therapy with Dabrafenib plus Trametinib followed by surgical resection and a further 40 weeks of adjuvant therapy to complete 1 year in total." (PMID 40857557, 2025). "Firstly, the common BRAF mutation in melanoma can lead to resistance to BRAF inhibitors." (PMID 40699636, 2025). "Histology of a skin lesion confirmed metastasis of the BRAF-mutated malignant melanoma." (PMID 40689241, 2025). "However, the use of ML, both alone and in combination with chemotherapeutic drugs, exhibited strong synergistic effects in the treatment of BRAF-mutated A-2058 and WM 266-4 melanoma cell lines, as well as in U-87 and U-118 glioblastoma cells." (PMID 40004697, 2025).
melanoma (continued). "Moreover, BRAF-mutated melanomas with increased TERT expression were observed to be resistant to BRAF and MEK inhibitors." (PMID 40361989, 2025). "In our patient with recurrent melanoma, we questioned whether a BRAF V600E mutation had developed and whether targeting this mutation would be considered in his next line of treatment." (PMID 39940799, 2025). "However, studies have shown Vemurafenib (BRAF inhibitor) alters uptake of Fludeoxyglucose (FDG) in melanoma cells harbouring the BRAFV600E mutation, with changes being noted particularly in Glucose transporters 1/3 (GLUT1/3)." (PMID 39671021, 2025). "Dermoscopic ulceration was also observed to be more frequent in BRAF-mutated melanomas." (PMID 41010758, 2025). "Similarly, CDKN2A mutations or deletions are associated with adverse outcomes in BRAF-mutant melanoma." (PMID 40332392, 2025). "The melanoma lines, M14 and A2058, were chosen as they both carry the BRAF V600E mutation." (PMID 40558548, 2025). "Survival outcomes for melanoma patients with BRAF mutations have increased with management by BRAF and MEK inhibitors, and the use of combination therapies with these drugs has demonstrated even better overall survival rates with delayed resistance development." (PMID 40002300, 2025). "Instead, a comparative analysis of melanoma cell lines derived from primary tumors or the metastasis of human, canine, and equine species showed comparable mutations in proto-oncogenes BRAF, NRAS, and KIT, which are well-known factors regulating proliferation and apoptosis in human melanoma." (PMID 40563676, 2025). "Of particular note, this effect was larger in patients with BRAF-mutated melanoma, accounting for ca 40% of all MM, which has a more aggressive phenotype, with distinct immune interactions, propensity for haematogenous spread and the development of brain metastases." (PMID 41194666, 2025). "Meanwhile, BRAF is the most predominant genetic mutation in melanoma." (PMID 41315179, 2025). "Conversely, resistance to mitogen-activated protein kinase (MAPK) pathway inhibitors has generally been associated with increased FAO in BRAF mutated melanoma cells and this agreement with our finding which decreases these free fatty acids due to the increase of fatty acids oxidation." (PMID 39886047, 2025). "One study identified acquired oncogenic mutations in NRAS and the loss of CDKN2A in BRAF-V600E-mutant melanoma tumors from two patients who progressed on BRAF/MEK inhibitors, suggesting that the reactivation of MAPK and the activation of cell cycle pathways contribute to resistance." (PMID 40282469, 2025). "Similarly, BRAF V600E mutations in melanoma indicate likely benefit from BRAF inhibitors, in contrast to wild-type tumors where efficacy is limited." (PMID 41295218, 2025). "Furthermore, the mutation rate of melanoma is one of the highest among different cancers, with mutations seen primarily in the BRAF, NRAS, and MEK genes, increasing the immunogenicity of tumor cells." (PMID 39941844, 2025). "The most frequent somatic mutation in melanoma is in the BRAF gene." (PMID 41010758, 2025). "The LOXL3-SNAIL1-PRRX1 axis may promote the acquisition of malignant phenotypes in melanoma, particularly in the presence of oncogenic BRAF mutations, thereby enhancing tumor cell invasion and migration." (PMID 41250755, 2025). "Additionally, the molecular heterogeneity of COM has been documented in previous studies, identifying subtypes with profiles similar to human melanomas with BRAF mutations or NF1 deficiency." (PMID 40647405, 2025).
melanoma (continued). "In line with previous reports, we found that the histological ulceration—the third most powerful indicator of survival after melanoma thickness and mitotic activity —was significantly more frequent in BRAF-mutated than in melanoma with other genes mutated or wild type." (PMID 40867317, 2025). "About 50% of melanomas are characterized by the presence of BRAF-activating mutations." (PMID 39859367, 2025). "The BRAF-activating mutations are prevalent in over 50% of melanoma cases." (PMID 40343301, 2025). "Of the cases with BRAF WT melanoma, nearly 15 to 30 percent have an NRAS mutation." (PMID 39940799, 2025). "Background/Objectives: BRAF mutation is the most frequent somatic mutation in melanoma." (PMID 41010758, 2025). "In melanoma, the BRAF mutation is associated with young age and intermittent sun exposure." (PMID 41202496, 2025). "In patients with stage III melanoma with BRAF V600E or V600K mutations, the phase III COMBI-AD trial demonstrated that adjuvant dabrafenib plus trametinib significantly improved relapse-free survival and overall survival compared with placebo at three and five years of follow-up." (PMID 41295253, 2025). "Blue-white veil was more frequently observed in BRAF-mutated melanomas." (PMID 41010758, 2025). "Interestingly, melanoma and thyroid cancer share a common genetic alteration, such as the BRAF V600E mutation." (PMID 41487768, 2025). "Research indicates that BRAF mutations are present in up to 50% of melanoma cases." (PMID 40236344, 2025). "In China, approximately 23.7% of patients with melanoma harbor BRAF mutations." (PMID 40861456, 2025). "For example, HER2-positive breast cancer and ALK-positive lung adenocarcinoma may increase RN risk, BRAF-mutated melanoma has been linked to a lower incidence." (PMID 41228337, 2025). "BRAF inhibitors are first-line treatments for melanoma patients with the BRAF V600E mutation." (PMID 41198656, 2025). "Melanomas can be further classified into four genomic subtypes based on the presence of specific driver mutations, namely B-Raf Proto-Oncogene (BRAF)-mutant, neuroblastoma RAS viral oncogene homolog (NRAS)-mutant, neurofibromatosis type I (NF1)-loss, and triple wild-type (TWT)." (PMID 40867277, 2025). "Building on this premise, the present study investigates whether treatment with BRAF/MEKi in melanoma may be associated with previously unrecognized cAEs." (PMID 40507236, 2025). "Somatic BRAF mutations are commonly observed in melanoma, thyroid cancer, and lung cancer." (PMID 40896440, 2025). "On this basis, the pharmacological inhibition of SCD1, in a BRAF-mutated melanoma context, showed a restored response to target therapy in 3D cultures and could be considered a new potential biomarker in treatments of melanoma CSCs." (PMID 40573249, 2025). "Within both melanoma and CRCs, the most common form of mutation is BRAF V600E." (PMID 40447784, 2025). "Of patients with stage III/IV BRAF-mutated melanoma, 20% (n = 372/1896) received immunotherapy only, 31% (n = 583/1896) received targeted therapy only, 20% (n = 383/1896) received immunotherapy and targeted therapy, and 29% (n = 558/1896) received neither immunotherapy nor targeted therapy." (PMID 40902091, 2025). "Indeed BRAF mutations frequently co-occur with inactivation of PTEN in melanomas, eliciting activation of the proproliferative MAPK pathway and PI3K/AKT/mTOR signaling, respectively." (PMID 39636745, 2025). "In this cohort, only 30% of patients had a BRAF V600 mutation, which represents the higher age of our cohort, since in the elderly there is a lower percentage of BRAF V600 mutations in melanoma; in the total population, approximately 50% of MBM patients have a BRAF V600 mutation." (PMID 40485242, 2025). "In particular, melanoma patients harboring BRAF and NRAS mutations may benefit from therapies targeting ACKR2." (PMID 40248897, 2025). "If confirmed, targeting ACKR2 could represent a beneficial therapeutic approach in BRAF/NRAS-mutated melanoma patients." (PMID 40248897, 2025).